OR1C1 (olfactory receptor family 1 subfamily C member 1)
Description:
Odorant receptor.
Synonyms: TPCR27; HSTPCR27; OR1-42; OR1.5.10; ORL211
Tractability: Small molecule: it belongs to a druggable protein family. Antibody: its Gene Ontology location is reachable by antibodies, with high confidence; UniProt places it where antibodies can reach, with medium confidence; UniProt predicts a signal peptide or a membrane-spanning region.
Gene: Protein-coding gene on chromosome 1 (247,754,846 to 247,760,556, reverse strand). Ensembl gene ENSG00000221888.
Subcellular location: Cell membrane
Pathways (Reactome):
Sensory Perception: Expression and translocation of olfactory receptors; Olfactory Signaling Pathway
Gene Ontology:
Molecular function: olfactory receptor activity; G protein-coupled receptor activity
Biological process: sensory perception of smell; signal transduction; detection of chemical stimulus involved in sensory perception of smell; G protein-coupled receptor signaling pathway
Cellular component: membrane; plasma membrane
Genetic constraint (gnomAD): Loss-of-function variants: 0 observed, 0.26 expected, observed/expected ratio (o/e) 0, 90% interval 0 to 1.87. That is too few expected variants to judge how well the gene tolerates losing a copy. Missense variants: 403 observed, 399.09 expected, observed/expected ratio (o/e) 1.01, 90% interval 0.93 to 1.1. Synonymous variants: 152 observed, 160.93 expected, observed/expected ratio (o/e) 0.94, 90% interval 0.83 to 1.08.
Homologues: Orthologues: chimpanzee OR1C1 (98% identical), macaque OR1C1 (93% identical). Paralogues in human: OR1F1 (57% identical), OR7C2 (52% identical), OR1G1 (52% identical), OR7A17 (52% identical), OR7C1 (52% identical), OR1E1 (52% identical), OR1J4 (51% identical), OR1E2 (51% identical), OR1L3 (51% identical), OR1J1 (50% identical), OR1M1 (50% identical), OR7A5 (50% identical), and 116 more.
Diseases named in the same sentence as OR1C1 in open-access papers:
OR1C1 is named in the same sentence as 1 disease in open-access papers, as found by Europe PMC text mining. Sharing a sentence is not in itself a finding about the gene and the disease. The quoted sentences say what the papers report.
cancer (1 paper, 2022). A tumor composed of atypical neoplastic, often pleomorphic cells that invade other tissues. "In order to verify reliable GRSDMs, 22 specific DNA methylation genes related to prognosis obtained in the training set were verified on 11 sets of GEO data, and 8 of the specific DNA methylation genes (DGRK, F2RL3, GRK5, NECAB2, OR1C1, OR2L13, OR6F1, and PIK3R6) had been verified in pan-cancer." (PMID 35885996, 2022).